PRDX1 (peroxiredoxin 1)
Diseases named in the same sentence as PRDX1 in open-access papers (continued):
Sharing a sentence is not in itself a finding about the gene and the disease.
tumor (continued). "Numerous genes known to be highly expressed in proliferating cells (Tfrc, metallothioneins genes) were upregulated by the HPD while tumor suppressor genes (Ppp2r2a, Ndrg1 and Prdx1) were downregulated by the HPD (q < 0.01)." (PMID 28137254, 2017). "To determine if Prdx1 mRNA levels correlate with elevated Prdx1 expression in patient tumor samples, we used the Oncomine mRNA database of human normal and tumor samples." (PMID 29190947, 2017). "Prdx1 has been viewed as a tumor-suppressor as Prdx1-knockout mice exhibit a shortened life span due to the development of hemolytic anemia and cancer." (PMID 24009050, 2013). "Prdx1 regulates the tumor-suppressive function of PTEN by forming a complex with it, and inhibits inactivation of the lipid phosphatase of PTEN induced by H2O2." (PMID 24009050, 2013). "In the present study, the presence of PRDX1 in TIF from NSCLC patients was verified by Western blot to be elevated in abundance in tumor TIF as compared to NAT TIF." (PMID 23914992, 2013). "Peroxiredoxin 1 (PRDX1) functions as a tumor suppressor and has a cytoprotective role in breast cells." (PMID 23971998, 2013). "Anti-tumor drugs like histone deacetylase inhibitors (HDACIs) activate Prdx1, a tumor suppressor, which leads to apoptosis." (PMID 21933383, 2011). "A further investigation is needed to gain a deeper insight into the Prdx1 regulation by MPA through HDACs inhibition interaction with Prdx1 and its role in anti-tumor activities." (PMID 21933383, 2011). "Under a hypoxia/reoxygenation condition, which mimics tumour microenvironment, Keap1 expression is decreased whereas Nrf2 and peroxiredoxin-1 (Prx1) up regulated, resulting in removal of ROS and protection of cancer cells." (PMID 24281078, 2010). "In summary, the data show that IFI44 acts as an oncogene in ccRCC, promoting tumor progression through its interaction with PRDX1 while also shaping an immunosuppressive microenvironment, and suggest that IFI44 is a promising biomarker of prognosis and candidate therapeutic target for ccRCC." (PMID 41799288, 2026). "On one hand, PRDX1 promotes cholesterol efflux in macrophages, which may fuel tumor cell proliferation." (PMID 41601657, 2026). "We next assessed whether PRDX1 could affect the macrophages phagocytosis of tumor cells by flow cytometry." (PMID 41306557, 2025). "However, the role of PRDX1 in regulating homologous recombination pathway response is a likely explanation for the poor prognosis of high-expressing PRDX1 tumours." (PMID 40387816, 2025). "In bulk RNA-seq datasets, PRDX1 expression was notably elevated in muscle-invasive BLCA and showed a strong association with disease progression, as well as with advanced tumor grade and stage." (PMID 41019038, 2025). "Notably, in contrast to the attenuated M2 polarization observed in macrophages co‐cultured with PRDX1‐knockdown tumor cells, those co‐cultured with PRDX1‐overexpressing cells or treated directly with lactate exhibited a pronounced M2 phenotype." (PMID 41306557, 2025). "Consequently, the definitive causal role of STMN1/PRDX1 in regulating LDHA/GPX4 and driving tumor progression in a physiological context remains to be established." (PMID 41403955, 2025). "Additionally, PRDX1 regulates the function of immune cells, promoting tumor immune evasion and influencing patient prognosis." (PMID 40256656, 2025). "We observed markedly increased PRDX1 levels in both BLCA tissues and cultured cell lines, where elevated expression linked to worse patient outcomes and more aggressive clinical characteristics, including higher tumor grades and stages." (PMID 41019038, 2025). "Further analysis revealed that the significant cell communication between PRDX1-positive monocytes and fibroblasts could potentially promote the immune evasion mechanism and immune suppression within the tumor microenvironment." (PMID 40256656, 2025).
tumor (continued). "Similarly, knockdown of PRDX1 in RAW264.7 augmented the cytotoxicity of tumor‐infiltrating CD8+ T cells as shown by enhanced expression of TNF‐α and GzmB, concurrent with reduced expression of PD‐1." (PMID 41306557, 2025). "Similarly, low PRDX1/ATM co-expression was associated with better PFS and overall survival (OS) compared to tumours with high PRDX1/high ATM expression." (PMID 40387816, 2025). "Notably, tumor growth was markedly suppressed in the Bacilli + sh-PRDX1, Bacilli + 2-DG, and Bacilli + PD-1 groups, with final tumor volumes comparable to those observed in the Control group." (PMID 40693141, 2025). "PRDX1 expression correlated with tumor aggressiveness and poor prognosis in public BLCA cohorts." (PMID 41019038, 2025). "Since T lymphocytes function as the predominant tumoricidal effector cells, we hypothesized that PRDX1 ablation in macrophages enhanced anti‐tumor immunity by inducing an M1 polarization phenotype." (PMID 41306557, 2025). "As a result, a total of 183 tumours were suitable for PRDX1 IHC analysis." (PMID 40387816, 2025). "As DNA repair is intricately connected to the development of drug resistance in tumor cells 46, it could be inferred that PRDX1 may influence the sensitivity of EGFR-TKI treatment in LUAD patients via genomic instability." (PMID 40303499, 2025). "Notably, PRDX1 knockout macrophages inhibited syngeneic tumor growth and enhanced sensitivity to anti‐PD‐1 therapy in vivo." (PMID 41306557, 2025). "Elevated PRDX1 expression is associated with poor prognosis and reduced NK cell infiltration, indicating that PRDX1 may serve as a key regulator of tumor immune evasion and represents a promising therapeutic target in HCC." (PMID 40693141, 2025). "In the Matrigel invasion assay, PRDX1 overexpression markedly enhanced invasion, while knockdown of PRDX1 resulted in an invasion rate that was only 31% of that observed in control cells, suggesting a strong role of PRDX1 in facilitating tumor cell invasiveness." (PMID 40693141, 2025). "Furthermore, hypoxia is a characteristic feature of the tumour microenvironment and NK cells are more sensitive to hydrogen peroxide compared to T or B cells due to decreased expression of peroxiredoxin-1 (PRDX1)." (PMID 38223411, 2024). "The tumor-promoting effect of PRDX1 in CRC was mainly due to the inhibition of ferroptosis." (PMID 39430237, 2024). "Interestingly, the addition of TBHQ or Fer-1 significantly attenuated the anti-tumor effects of PRDX1 silencing." (PMID 39430237, 2024). "Finally, PPIA and PRDX1 were both detected and overexpressed in tumor-derived extracellular vesicles." (PMID 38252632, 2024). "While the role of PRDX1 in the DNA damage and repair processes as well as in tumorigenesis has been reported, future work will be needed to elucidate in which conditions it functions as a tumor suppressor or, on the contrary, facilitates tumor development." (PMID 37259925, 2023). "Inhibiting PRDX1, in this context, exerts anti-tumor effects." (PMID 37781072, 2023). "It is expected that arsenite will sensitise tumour cells, which are defective in the PRDX1 function, and that increasing the doses of arsenite could have additional benefits by triggering the degradation of GLUT3, thereby starving the cells of glucose." (PMID 38067110, 2023). "It has been reported that PRDX1 can reduce ROS and inhibit tumor cell apoptosis." (PMID 37227568, 2023). "However, histone deacetylase inhibitor FK228 is known to activate Prdx1, partly via the regulation of promoter histone acetylation, thereby inducing apoptosis and repressing tumor growth." (PMID 37781072, 2023). "Thus, we further explored the difference in tumor microenvironment between PRDX1/5/6-low and PRDX1/56-high." (PMID 35350568, 2022). "The role of PRDX1 in suppressing tumours has been confirmed in Prdx1-knockout mouse models." (PMID 34215320, 2021).
tumor (continued). "Moreover, PRDX1 overexpression had a significant association with advanced TNM stage (OR = 2.26, 95% CI: 1.24-4.13, P = 0.008, random effects) and poor tumor differentiation (OR = 0.59, 95% CI: 0.44-0.81, P = 0.001, fixed effects)." (PMID 33747258, 2021). "PRDX1 overexpression was related to poor prognosis and tumor invasiveness in solid cancers." (PMID 33747258, 2021). "Jiang reported that LINC00460 could effectively induce epithelial-mesenchymal transition in Peroxiredoxin-1 dependent manner, enhancing the tumor cell proliferation and metastasis of HNSCC." (PMID 34880875, 2021). "Fifteen cohorts comprising 1,907 patients reported the relationship between PRDX1 expression and tumor size, and the pooled results indicated that high expression of PRDX1 was correlated with large tumor size (OR = 1.69, 95% CI: 1.07-2.68, P = 0.025, random effects)." (PMID 33747258, 2021). "PRDX1 cooperates with thioredoxin in inhibiting ROS-induced tumor cell apoptosis and promoting tumor cell survival by involving different types of kinases and enzymes, such as apoptosis signal-regulating kinase 1, p66Shc, and glutathione S-transferase pi (GSTpi)/c-Jun NH2-terminal kinase (JNK)." (PMID 33747258, 2021). "Tumours arise both in Prdx1−/− and Prdx1± mice with an incidence ratio of 2:1." (PMID 34215320, 2021). "PRDX1 directly effects tumor suppression by eliminating ROS and preventing oxidative damage to DNA." (PMID 33747258, 2021). "Additionally, the applicability of the observed effects of Prdx1 on the NEDD9-Aurora A-HDAC6 signal axis to other tumor aspects requires future study." (PMID 32357862, 2020). "However, in COAD, although moderate expression of PRDX1 was also shown in the tumor cells, the location was different and PRDX1 was found to be positive only in the cytoplasm/membrane of the tumor cells in all the eight COAD tissues." (PMID 32231717, 2020). "The mice tumor weight and volume also decreased significantly after inhibition of Prdx1." (PMID 32357862, 2020). "While these novel data imply that targeting JNK may be a strategy to inhibit tumor desmoplasia, they also suggest that targeting PRDX1 in cancer could promote unwanted tumor desmoplasia." (PMID 31419957, 2019). "In addition, only 12.5% (2 out of 16) of the patients with detectable tumor cells in their blood had detectable PRDX1-positive CTCs." (PMID 31370904, 2019). "Some studies have shown that PRDX1 serve as tumor suppressor in several types of cancers, but other studies prove that PRDX1 may promote tumor growth." (PMID 29492195, 2018). "This newly identified PRDX1-Akt pathway might argument our knowledge in ROS mediated tumor initiation and promotion." (PMID 29492195, 2018). "Maintaining the redox function of Prdx1 is critical for its tumor suppressive functions." (PMID 29190947, 2017). "Modified Txn system function and post-translational regulation may therefore play a significant role in pancreatic tumorigenesis by altering Kras effector phosphorylation and inhibiting the tumor suppressive redox functions of Prdx1." (PMID 29190947, 2017). "PRDX1 oligomer could interact with the c‐Myc oncogene and suppresses its transcriptional activity, which in turn inhibits tumourigenesis and promotes tumour cell apoptosis." (PMID 27653015, 2017). "Additionally, our data suggests that during the earlier stages of neoplasia, the way Prdx1 functions and responds to oxidative stimuli is altered because it is post-translationally modified and the expression of Txn and Srxn is suppressed." (PMID 29190947, 2017). "Inhibition of Prdx1 peroxidase activity will therefore alter its tumor suppressive functions." (PMID 29190947, 2017). "However, a recent study suggests that PRDX1 functions as a nuclear erythroid 2‐related factor 2 (Nrf2) dependently inducible tumour suppressant in K‐ras‐driven lung tumourigenesis by prohibiting ROS/ERK/cyclin D1 pathway activation." (PMID 27653015, 2017).
tumor (continued). "Its hyperoxidation could also contribute to elevated Prdx1 secretion and the perpetuation of inflammation by secreted Prdx1 as the tumor progresses." (PMID 29190947, 2017). "These malignancies are associated with low expression of PRDX1, which suggests that PRDX1 may function as a tumor suppressor." (PMID 25632391, 2015). "It is reported that PRDX1 could be secreted from tumor cells and extracellular PRDX1 could induce the secretion of proinflammatory cytokines such as TNF-α and IL-6." (PMID 25024510, 2014). "Moreover, our results suggest that any prospective PRDX1 inhibitors should be explored with caution in ER-positive breast cancer due to the potential to convert tumor cells to a more aggressive phenotype with a worsened outcome." (PMID 25011585, 2014). "While comparing the expression profile of Prdx1 in ESCC tissues with other tumor types, there may be various significant differences which are notable." (PMID 24009050, 2013). "Deletion of PRDX1 has been shown to promote tumor growth in mice." (PMID 23971998, 2013). "In addition, our finding of elevated levels of PRDX1 in the serum of EOC patients versus normal/benign patients warrants further evaluation as a tumor specific biomarker for EOC." (PMID 21980378, 2011). "However, CA appears to suppress the expression of several of these genes, including CKS1B, CCNA2, and CCND1, while simultaneously promoting the upregulation of tumor-suppressor genes, such as peroxiredoxin 1 (PRDX1) and cyclin-dependent kinase inhibitor 1 (CDKN1A, also known as P21)." (PMID 41003013, 2025). "Thus, targeting PRDX1 should sensitize tumours to DNA-damaging agents." (PMID 40387816, 2025). "Furthermore, PRDX1 facilitates hepatocyte autophagy, contributing to tumor advancement." (PMID 41403955, 2025). "While not previously associated with astrocytes, peroxiredoxin‐1 (PRDX1) is an intracellular enzyme with antioxidant activity reported to be secreted by tumor cells; and prolyl isomerase (PPIA), although cytoplasmic, is secreted as a defense mechanism in response to oxidative stress." (PMID 37303123, 2023). "Moreover, a study demonstrated that PRDX1 could promote the tumor inhibition effects of PTEN by binding PTEN and protecting it from H2O2-induced inactivation." (PMID 37198696, 2023). "Inferring low expression of PRDX1 may have an inhibitory effect on tumor progression." (PMID 37842089, 2023). "However, modulation of PRDX1 splicing using NBTs may be a more viable therapeutic approach as PRDX1 is an essential gene involved in mitigation of oxidative stress and tumor suppression." (PMID 36250017, 2022). "Compared with PRDX1/5-high patients, we found an increase in increased immune cell infiltration, HLA molecules, chemokines, cytolytic activity-related genes and immune checkpoint molecules in PRDX1/5-low patients, indicating that PRDX1/5-low exhibited a hot tumor state." (PMID 35350568, 2022). "Moreover, any possible PRDX1 inhibitors should be carefully explored in ER-positive breast cancer because they may transform tumor cells into a more aggressive phenotype with poor prognosis." (PMID 33747258, 2021). "Importantly for this work, previous publications have indicated that PRDX1 is markedly upregulated in malignant mammary lesions, as we confirm in our study, which might suggest the tumour-promoting properties of PRDX1." (PMID 30287919, 2018). "Therefore, understanding the role of Prdx1 in neoplasia and cancer may require determination of the mechanisms that regulate Prdx1 nuclear localization and secretion." (PMID 29190947, 2017). "Interestingly, silencing PRDX1 leads to increased levels of tumour suppressor genes LKB1 and p‐AMPK, and decreases the oncogene Aurora A expression, suggesting that PRDX1 may affect carcinogenesis." (PMID 27653015, 2017).
tumor (continued). "Furthermore, PRDX1 is up‐regulated in NSCLC tissue interstitial fluid, and high level of PRDX1 expression is related with lymph node metastasis and tumour differentiation, suggesting that PRDX1 may act as a marker of neoplastic progression." (PMID 27653015, 2017). "Proteomic signatures highlighted AREG, JUN, and ITGA6 can track skin damage, while CST5 and PRDX1 correlated with the preservation." (PMID 42143604, 2026). "Peroxiredoxin 1 (PRDX1), a key antioxidant enzyme that is frequently overexpressed in HCC, enables tumor cells to neutralize excessive reactive oxygen species (ROS), thereby sustaining survival and conferring therapeutic resistance." (PMID 41683534, 2026). "Pseudotime trajectory analysis positioned OxP-Mac as an early-state population branching into tumor-specific subsets (ALOX5AP+, HERPUD1+ and PRDX1+LA-Mac), suggesting differentiation plasticity." (PMID 41601657, 2026). "The knockdown of PRDX1 exerts a synergistic effect when combined with EGFR-TKI treatment, potently suppressing tumor growth." (PMID 40303499, 2025). "The crosstalk between PRDX1 and various signaling pathways was previously established including PTEN/AKT signaling and TRAF6 ubiquitin ligase signaling, exerting tumour suppressive roles." (PMID 40387816, 2025). "Collectively, these in vivo findings confirm that Bacilli infection enhances PRDX1 expression and glycolytic reprogramming in HCC, leading to suppression of NK cell-mediated cytotoxicity and promoting tumor immune evasion." (PMID 40693141, 2025). "In conclusion, targeted deletion of PRDX1 enhances anti‐tumor immunity in CRC by reprogramming the immunosuppressive TAMs, revealing a novel role of PRDX1 as a potential drug target during anti‐tumor immunotherapy." (PMID 41306557, 2025). "PRDX1, a primary target of peroxisome-derived H2O2, supports tumor growth and angiogenesis in PC3-M xenografts by promoting vascular endothelial growth factor (VEGF) expression in a Toll-like receptor 4 (TLR4)-dependent manner." (PMID 40647540, 2025). "This study reveals the key role of PRDX1 in BRCA progression, mainly through the regulation of the tumor microenvironment and immune escape mechanisms." (PMID 40256656, 2025). "PRDX1 was found to be markedly upregulated in both HCC patient samples and Bacilli-infected tumor models." (PMID 40693141, 2025). "In accordance with this, overexpression of PRDX1 can augment NK cell and CAR-NK-cell anti-tumour activity under oxidative stress conditions." (PMID 38223411, 2024). "The second module (M2) was composed of multiple metabolism-relevant phosphoproteins like PGK1, PSMF1, PRDX1, and TOM1, they showed lower expressions in the tumor tissues, especially the high RR tumor tissues." (PMID 38609408, 2024). "Considering the significant clinical relevance of PRDX1 in CRC, we investigated the effect of PRDX1 on tumor cell growth in vitro." (PMID 39430237, 2024). "Knockdown of PRDX1 attenuated the up-regulation of GADD45G and γ-H2AX with Celastrol or compound 19-048 treatment, which is consistent with the efficacy assessment for tumor volume and weight." (PMID 36732502, 2023). "In the current study, we set out to examine the levels of both PRDX1 and PRDX2 in GBM and non-tumor (NT) brain tissues." (PMID 37566013, 2023). "Both PRDX1 and PRDX2 were upregulated in GBM compared to non-tumor brain tissues and their considerable amounts were observed in GBM cells." (PMID 37566013, 2023). "In the tumor microenvironment, HCC patients with low PRDX1 expression had more significant infiltration levels of M0 macrophages, M1 macrophages, CD4+ Th1 cells, CD4+ Th2 cells, myeloid dendritic cells, monocytes, and lymphoid progenitor cells." (PMID 37842089, 2023). "PRDX1, a member of the peroxiredoxin (PRDX) family, has been demonstrated to preserve and boost the tumor inhibitory function of PTEN by binding PTEN and preventing PTEN oxidation under benign oxidative stress." (PMID 37198696, 2023).